TET3 (tet methylcytosine dioxygenase 3)
Diseases named in the same sentence as TET3 in open-access papers (continued):
Sharing a sentence is not in itself a finding about the gene and the disease.
ovarian carcinoma (continued). "Finally, the expression of TET3 in ovarian cancer was investigated by quantitative real-time PCR and immunohistochemistry." (PMID 33391417, 2021). "We identified that TET3 level in ovarian cancer tissues were lower than in normal ovarian tissues." (PMID 33391417, 2021). "Additionally, TET3 expression was decreased in ovarian cancer tissues, acted as a suppressor of ovarian cancer by demethylating miR-30d precursor gene promoter to block TGF-β1-induced epithelial-mesenchymal transition." (PMID 32209730, 2020). "The relationship of TET3 and ovarian cancer progression is understudied." (PMID 31656201, 2019). "To verify the expression pattern of TET3 in ovarian cancer, we analyzed TET3 mRNA expression levels by integration of 14 GEO datasets (GSE18520; GSE19829; GSE23554; GSE26193; GSE27651; GSE30161; GSE32062; GSE40595; GSE44104; GSE51373; GSE54388; GSE63885; GSE65986; GSE9891)." (PMID 31656201, 2019). "In ovarian cancer, TET3 is reported as oncogene or tumor suppressor during tumorigenesis." (PMID 31656201, 2019). "Previous studies indicated that TET3 is overexpressed in ovarian cancer tissues." (PMID 31656201, 2019). "It will be fascinating to test in the future whether targeting TET3 leads to new treatment options of ovarian cancer especially platinum resistance ovarian cancer." (PMID 31656201, 2019). "In conclusion, here we firstly indicated the role of TET3 in ovarian cancer progression." (PMID 31656201, 2019). "Finally, the relationships of TET3 expression to clinic-pathological parameters of ovarian cancer were investigated with a tissue microarray using immunohistochemistry." (PMID 27141829, 2016). "Since TGF-β1 could induce EMT in ovarian cancer cells in our previous study, we speculated that TET3 might participate in TGF-β1-triggered EMT." (PMID 27141829, 2016). "TET3 expression level in various histopathological subtypes of ovarian cancer was further analyzed." (PMID 27141829, 2016). "Therefore, we use meta-analysis in Oncomine platform to assess TET3 gene expression in ovarian cancer, followed by integration analysis using a larger sample size including 14 studies in GEO datasets, and further validated with gene expression from TCGA and GTEx." (PMID 31656201, 2019). "The study provided the new mechanistic evidence about TET3/miR-145/HK2 pathway in the anti-Warburg effect of berberine, providing evidence for berberine to become a candidate drug for clinical treatment of ovarian cancer." (PMID 33391417, 2021). "Our study demonstrated that proteins related with TET3 are mainly DNA methylase or demethylases such as DNMT, and most of these genes showed amplification in ovarian cancer." (PMID 31656201, 2019). "The levels of 5hmC were shown to be significantly increased in TET1-overexpressing ovarian cancer cells, which was consistent with the results obtained using transient TET1 or TET3 overexpression." (PMID 29156803, 2017). "In our study, we found that TET3 was decreased in ovarian cancer tissues, as well as in TGF-β1-treated ovarian cancer cells." (PMID 27141829, 2016). "TET3 was downregulated during TGF-β1-initiatd epithelial-mesenchymal transition (EMT) in SKOV3 and 3AO ovarian cancer cells." (PMID 27141829, 2016). "In current study, we observed that TET3 was upregulated in ovarian cancer tissues compared with normal controls." (PMID 31656201, 2019). "When treatment of acquired platinum-resistant ovarian cancer with guadecitabine (DNMT inhibitor) and carboplatin, TET3 expression is dramatically up-regulated (logFC = 1.04, GSE102118, data not shown), indicating that TET3 can have a role with the combination of DNMT or other methylases." (PMID 31656201, 2019). "Overexpression of TET3 reversed TGF-β1-induced EMT phenotypes including the expression pattern of molecular markers (E-cadherin, Vimentin, N-cadherin, Snail) and migratory and invasive capabilities of ovarian cancer cells." (PMID 27141829, 2016).
ovarian carcinoma (continued). "Consistently, TET3 was upregulated in ovarian cancer tissues compared with normal controls." (PMID 35755313, 2022). "Our results indicated that TET3 declined in TGF-β1 stimulation and TET3 overexpression inhibited TGF-β1-induced EMT and EMT-mediated metastasis of SKOV3 and 3AO cells by demethylating miR-30d precursor gene, indicating a novel mechanism of epigenetic regulation in ovarian cancer." (PMID 27141829, 2016). "miR-30d was identified as a downstream target of TET3, and TET3 overexpression resumed the demethylation status in the promoter region of miR-30d precursor gene, resulting in restoration of miR-30d (an EMT suppressor of ovarian cancer cells proven in our previous study) level in TGF-β1-induced EMT." (PMID 27141829, 2016).
endometriosis (9 papers, 2018 to 2025). The growth of functional endometrial tissue in anatomic sites outside the uterine body. "In the current work, we used publicly available human scRNA-Seq data combined with genetic and pharmacological approaches to identify pathogenic macrophages characterized by TET3 overexpression in endometriosis." (PMID 39141428, 2024). "Our results defined TET3-overexpressing macrophages as key pathogenic contributors to and attractive therapeutic targets for endometriosis." (PMID 39141428, 2024). "Here, we report identification of pathogenic macrophages characterized by TET3 overexpression in human endometriosis lesions." (PMID 39141428, 2024). "Further, myeloid-specific TET3 loss reduced endometriosis in mice." (PMID 39484721, 2024). "Neurotrophic factors produced by macrophages, such as Netrin-1, insulin-like growth factor-1, and ten-eleven translocation 3 (TET3), play a role in the pain associated with endometriosis." (PMID 40508002, 2025). "In the current work, we identify pathogenic macrophages characterized by TET3 overexpression (herein referred to as Toe-Macs) in MASH, NSCLC, and endometriosis." (PMID 40794443, 2025). "In human endometriosis lesions, TET3 OE macrophages were predominantly found in 2 subpopulations that expressed some markers of “tissue-resident macrophages/PMs,” but did not express GATA6, a signature marker of LPMs of embryonic origin." (PMID 39141428, 2024). "The interplay between TET3 and IL-6 particularly underscores the importance of targeting TET3 in macrophages as a promising strategy to improve outcomes for patients with endometriosis." (PMID 39484721, 2024). "Targeting TET3 offers a promising strategy to modulate the inflammatory environment in endometriosis." (PMID 39484721, 2024). "In the current work, we provide critical mechanistic insights into TET3-mediated regulation of IL-1β and IL-6, 2 key cytokines with well-established roles in endometriosis." (PMID 39141428, 2024). "TGF-β1 and MCP1 are present in the peritoneal cavity of women with endometriosis, and macrophage exposure to these factors resulted in upregulation of TET3, thereby promoting their survival." (PMID 39484721, 2024). "We discover a specific population of disease-promoting macrophages characterized by TET3 overexpression and a potential new therapeutic agent for endometriosis, a life-impacting chronic inflammatory disease." (PMID 39141428, 2024). "Second, the TET3 OE macrophages in human endometriosis lesions were of monocyte origin, but were reprogrammed by the disease microenvironment to express some embryonic-lineage markers." (PMID 39141428, 2024). "First, an analysis of the human scRNA-Seq from an independent study demonstrated a significant rise in the proportion of TET3 OE macrophages in endometriosis compared with normal controls." (PMID 39141428, 2024). "First, the TET3 OE macrophages in human endometriosis lesions were of embryonic origin but lost GATA6 expression due to reprogramming by the disease microenvironment." (PMID 39141428, 2024). "Third, the TET3 OE macrophages in human endometriosis lesions were a mixture of both embryonic and monocyte origins." (PMID 39141428, 2024). "Particularly important was the finding that Bobcat339 selectively degraded TET3 and reduced endometriosis progression in mice." (PMID 39484721, 2024). "TET3 expression levels were higher in macrophages of endometriotic lesions compared with control endometrial tissue, implicating TET3 as a contributing factor in the chronic inflammation that occurs in endometriosis." (PMID 39484721, 2024). "In all groups with endometriosis, the 5hmC content was higher than the control level, while the active demethylase TET3 content was reduced and the methylase content remained unchanged." (PMID 34440202, 2021). "Curiously, we observed a positive correlation between TET3 expression and that of VHL in macrophages from MASH, NSCLC, and endometriosis, suggesting that TET3 may regulate VHL expression." (PMID 40794443, 2025).
endometriosis (continued). "Recent reports further demonstrated that Bobcat339 can trigger TET3 degradation and deplete TET3-overexpressing human macrophage-induced chronic inflammatory processes, underscoring the therapeutic potential of targeting TET3 in macrophages as a strategy for managing endometriosis." (PMID 40697650, 2025). "Finally, let-7a miRNA levels were increased by Tet3-KO or Bc treatment in mouse endometriosis tissues." (PMID 39141428, 2024). "Thus, Tet3 ablation in the myeloid compartment substantially reduces lesional TET3 OE macrophages, proinflammatory cytokine production, and endometriosis burden." (PMID 39141428, 2024). "TET3 acts as a positive regulator for the expression of proinflammatory genes, such as IL-6 and IL-1β, both of which play well-documented roles in the pathology of endometriosis." (PMID 39141428, 2024). "Furthermore, depleting TET3-overexpressing macrophages either through myeloid-specific Tet3 ablation or using Bobcat339 strongly inhibited endometriosis progression in mice." (PMID 39141428, 2024). "RNA-Seq analysis following TET3 knockdown revealed alterations in cytokine signaling and cell-death pathways, underscoring the therapeutic potential of targeting TET3 in macrophages as a strategy for managing endometriosis." (PMID 39484721, 2024). "Drawing from our scRNA-Seq and IHC investigations, which revealed a disease-specific correlation of TET3 OE macrophages, we postulated that these macrophages might contribute to the pathology of endometriosis." (PMID 39141428, 2024). "The interplay between TET3 and IL-6 suggests that TET3-overexpressing macrophages may drive the inflammatory response in endometriosis by modulating IL-6 signaling." (PMID 39484721, 2024). "TET3-overexpressing macrophages are abundant in endometriosis lesions." (PMID 39141428, 2024). "In this study, we describe the identification of TET3 OE macrophages in endometriosis." (PMID 39141428, 2024). "The content of active demethylase of the ten-eleven translocation protein TET3 decreased in groups with endometriosis: in group 3 the decrease was 20% (p < 0.05), in group 4 it was 22% (p < 0.05), in group 5 it was 23% (p < 0.05), and in group 6 it was 29% (p < 0.05)." (PMID 34440202, 2021). "Along those lines, endometriosis tissues have decrease expression of ten-eleven translocation genes (TET1, TET2, and TET3), which convert 5-methylcytosine to 5-hydroxymethlcytosine and play a role in changes in levels of 5-hydroxymethylcytosine marks in endometriosis tissues and blood." (PMID 30087267, 2018). "Ten–eleven translocation genes (TET1, TET2, and TET3) are downregulated in endometriosis." (PMID 29743986, 2018). "In endometriosis, signals from the DME (e.g., TGF-β1 and CCL2) drive TET3 overexpression, generating a unique Toe-Macs macrophage population that becomes dependent on elevated TET3 levels." (PMID 40794443, 2025). "In line with the high heterogeneity of endometriosis lesions within each individual and across individuals with endometriosis, TET3 OE macrophages were not uniformly distributed throughout disease tissue and varied in abundance across patients." (PMID 39141428, 2024). "Thus, the striking disease-specific cooverexpression of TET3 and VHL would likely increase the specificity of Bc action and explain, at least in part, the high efficacy and low toxicity of Bc in our mouse endometriosis therapy studies." (PMID 39141428, 2024).
glioblastoma (9 papers, 2012 to 2025). The most malignant astrocytic tumor (WHO grade IV). "It has been shown that TET1/2/3 expression is downregulated in glioblastoma and that TET3 levels are associated with a better prognosis in patients with glioblastoma." (PMID 40599235, 2025). "Low levels of TET1 and TET3 were also associated with reduced survival in glioblastoma." (PMID 22829908, 2012). "Intriguingly, increased TET3 expression inhibited growth and self-renewal in tumorigenic glioblastoma stem cells, indicating that TET3 has tumor suppressor function in the brain." (PMID 35396259, 2022). "Recently, epigenetic repression of histone marks (H4K16ac, H3K4me3, H3K9ac, H3K36me3, H3K4me1, H3K27ac) in TET3 gene has been postulated as a driver of glioblastoma development via genome-wide alteration of 5-hmC." (PMID 35494033, 2022). "In this study, the authors show that inhibition of TLX expression, achieved using a dendrimer nanovector-delivered siRNAs or viral vector-delivered shRNAs, reduces glioblastoma stem cells self renewal and in vivo tumour growth through activation of TET3." (PMID 26838672, 2016). "Moreover, ectopic overexpression of TET3 in a glioblastoma cell line was reported to impair cell growth and reduce tumor formation in immunodeficient mouse models." (PMID 35396259, 2022). "Moreover, TET3 functions as a potent tumor suppressor downstream of the TLX nuclear receptor to regulate growth and self-renewal in glioblastoma." (PMID 29849955, 2018).
Obesity (9 papers, 2020 to 2025). Accumulation of substantial excess body fat. "We observe a difference in the mRNA expression of Tet1 and Tet3 in the cerebellum in males exposed to maternal obesity compared with controls." (PMID 40373797, 2025). "Further, we have recently documented that CRISPR-mediated, agouti-related protein (AgRP) neuron-specific Tet3 ablation induces hyperphagia, systemic insulin resistance, obesity and type 2 diabetes." (PMID 38216792, 2024). "Moreover, we observed higher expression levels in SAT compared to OVAT for the erasers TET1, TET2, and TET3, while the expression is lower across tissue depots among subjects with obesity." (PMID 41030849, 2025). "This highlights the critical role of TET3 in the central control of obesity." (PMID 40620794, 2025). "In addition, we documented that CRISPR-mediated genetic ablation of Tet3 specifically in AgRP neurons in the mouse hypothalamus induced hyperphagia, systemic insulin resistance, obesity and type 2 diabetes." (PMID 38216792, 2024). "However, in maternal obesity, placental TET3 methylation is increased, without totally understanding its role in obesity." (PMID 32982666, 2020).
Hyperglycemia (8 papers, 2017 to 2025). An increased concentration of glucose in the blood. "The insufficiency of TET3 induced by maternal hyperglycemia conferred a predisposition to glucose intolerance in the next generation through hypermethylation of the glucokinase gene in pancreatic islets." (PMID 39695937, 2024). "We reported a chronic increase in TET3 expression in the livers of humans and mice with type 2 diabetes and that TET3 induced Hnf4a promoter demethylation leading to heightened hepatic glucose production and hence hyperglycaemia." (PMID 38216792, 2024). "We were the first to report that TET3 expression is increased in the livers of humans with type 2 diabetes and in mouse models of type 2 diabetes, contributing to hyperglycaemia." (PMID 38216792, 2024). "Among all the differentially expressed genes, Tet3 transcripts were detected significantly downregulated in hyperglycaemia oocytes." (PMID 35802824, 2022). "Offspring from genetically engineered Tet3+/− and Tet3−/− oocytes exhibited altered DNA methylation status of Gck and glucose intolerance, which was similar to those from hyperglycaemia oocytes." (PMID 35802824, 2022). "Hyperglycaemia directly compromised maternal oocytes’ Tet3 levels and further indirectly defected paternal DNA methylation reprogramming via TET3 insufficiency, finally causing the perturbations of insulin secretion gene expression and glucose intolerance in next generation." (PMID 35802824, 2022). "Additionally, a supplemental injection of exogenous Tet3 mRNA to mature oocytes abolished the effects of hyperglycaemia or Tet3 deletion." (PMID 35802824, 2022).
Anxiety (7 papers, 2020 to 2024). Intense feelings of nervousness, tension, or panic often arise in response to interpersonal stresses. "Here, we show that Bobcat339, a synthetic small molecule that controls TET3 in AgRP neurons, is able to mitigate anorexia nervosa and associated anxiety/depressive behaviors in a murine model." (PMID 37036983, 2023). "Other genes of interest include Pkce and Tet3, both of which have been affiliated with depression or anxiety-like behaviors." (PMID 37228107, 2023). "To date, studies using animal models carrying neurons with a disrupted TET3 gene have reported increased anxiety-like behavior, impaired spatial orientation and short-term memory, suggesting potential risks of TET3-related neurological disorders in humans." (PMID 39149518, 2024). "In the current work, we used a well-established mouse model of activity-based anorexia (ABA) to demonstrate that a small-molecule degrader of TET3 is able to effectively attenuate AN and anxiety/depressive-like behaviors, at least in part, via decreasing TET3 expression in AgRP neurons." (PMID 37036983, 2023). "They notice that Tet3 deletion in mature neurons induces a dysregulation of genes related to the HPA axes, which are generally regarded as susceptibility-related genes for anxiety, and increases IEGs’ expression in the hippocampus." (PMID 35563298, 2022). "Interestingly, our previous work revealed that Npas4 is epigenetically regulated in a conditional Tet3 KO mouse model that presents anxiety-like behavior and cognitive deficits." (PMID 32848656, 2020). "TET3, the most abundant of the three TET dioxygenases in the brain, has been shown to be relevant in modulating anxiety behavior in the hippocampus and the prefrontal cortex." (PMID 37108466, 2023). "Patients suffering from anxiety are usually accompanied by hypothalamic-pituitary-adrenocortical (HPA) axis hyperresponsiveness, and the role of TET3 in regulating HPA axis and neuronal activity has been illustrated." (PMID 35563298, 2022). "Antunes and co-workers identified that TET3 is required for maintaining the proper anxiety level and normal spatial cognitive function." (PMID 35563298, 2022).
lung cancer (7 papers, 2020 to 2025). A malignant neoplasm involving the lung. "To test this, we used a syngeneic lung cancer mouse model in combination with either myeloid-specific Tet3 KO (KO mouse model) or Bc." (PMID 40794443, 2025). "Subsequently, we examined the expression of TET3 protein in three different pathological subtypes of lung cancer cell lines (A549, SKMES1, NCIH460)." (PMID 39104395, 2024). "Using coimmunoprecipitation (co-IP) assays, TET3 was shown to form protein complexes with VHL in H1299 cells (a human lung cancer cell line) where VHL overexpression accelerated TET3 degradation." (PMID 39141428, 2024). "Although driver mutations of TETs are infrequent in lung cancer, with TET2 having a higher frequency of somatic mutations compared to TET1 and TET3, an altered expression of TETs has been observed." (PMID 35205708, 2022). "Either myeloid-specific Tet3 ablation or Bobcat339 treatment attenuated lung cancer progression." (PMID 41178715, 2025). "However, the expression changes in TETs, especially for TET2 and TET3, in lung cancer remain somewhat unclear, with conflicting observations for TET1 in cell lines and primary tumor models." (PMID 35205708, 2022).